PEAK1 (pseudopodium enriched atypical kinase 1)
Diseases named in the same sentence as PEAK1 in open-access papers (continued):
Sharing a sentence is not in itself a finding about the gene and the disease.
breast carcinoma (continued). "We also evaluated the correlation between PEAK1 levels and EMT gene signatures previously reported to be regulated by PEAK1 in mammary epithelial cells across a panel of breast cancer cell lines." (PMID 26267863, 2015). "Since TGFβ is a well-known inducer of EMT during both development and cancer progression, we sought to test the effects of TGFβ on PEAK1 and E-Cadherin expression in MCF10A cells alongside three cellular models of breast cancer." (PMID 26267863, 2015). "In the present study, we performed IHC for PEAK1 in 112 surgically resected breast cancer tissues and 43 adjacent non-tumor breast tissues." (PMID 34554318, 2022). "In the present study, PEAK1 expression was correlated with both Ki-67 and HER2 expression in breast cancer, suggesting that PEAK1 expression may predict chemosensitivity in breast cancer." (PMID 34554318, 2022). "We also found that PEAK1 is overexpressed in breast cancer tissues at significantly higher levels than adjacent non-tumor breast tissues." (PMID 34554318, 2022). "High expression of both SNAI2 and PEAK1 did not predict OS probability among breast cancer patients reporting enrichments in either innate or adaptive immune cell content." (PMID 34239043, 2021). "Additional patient sample staining revealed further that the cytoplasmic PEAK1 and nuclear SNAI2 expression within the stromal tissue of HER2-positive breast cancers can occur within the same fibroblastic cell types – a pattern not observed in the HER2-negative patient samples." (PMID 34239043, 2021). "Notably, the transcripts of PEAK1-suppressed MSC factors (i.e., TGFB3, VEGFA and CSF1) were significantly lower within breast cancer stroma (left three graphs)." (PMID 34239043, 2021). "We further determine that PEAK1-expressing MSCs promote the emergence of p-Akthigh/p-γH2AXlow, MCL1high/p-γH2AXlow and GRP78high/VIMhigh subpopulations within HER2-positive breast cancer cells that display resistance to lapatinib and are capable of enhancing tumorigenesis in vitro and in vivo." (PMID 34239043, 2021). "For example, in breast cancer, the PEAK1 expression pattern was not reflected in the relative mRNA levels, indicating that elevated PEAK1 expression in breast cancer cells must be mediated via a post-transcriptional or post-translational mechanism." (PMID 29449544, 2018). "Also, elevated expression of PEAK1 and VEGFR2 mRNA are highly correlated in many human cancers including breast cancer." (PMID 29872538, 2018). "Furthermore, we also report that PEAK1 expression levels significantly and positively correlate with EMT gene expression signatures in patient samples and ER- and/or HER2-positive breast cancer cell populations." (PMID 26267863, 2015). "Finally, we demonstrate that this PEAK1-dependent effect occurs via Src/MAPK signaling pathways and that PEAK1 upregulation/overexpression can desensitize breast cancers to the cytotoxic effects of Src kinase inhibition." (PMID 26267863, 2015). "Notably, PEAK1 expression correlated with decreased epithelial and/or increased mesenchymal gene expression patterns in HER2+ and/or ER/PR+ subtypes of breast cancer cells." (PMID 26267863, 2015). "Although PEAK1 has been previously reported to induce EMT-like responses in mammary epithelial cells, the contributions of PEAK1 to EMT in breast cancer have not been previously studied." (PMID 26267863, 2015). "Elevated PEAK1 expression across all breast cancer subtypes predicted a significant, though slight, increase in RFS, while elevated PEAK1 expression in HER2-positive breast cancers correlated with decreased RFS suggesting a role for PEAK1 in this more aggressive breast cancer subtype." (PMID 34239043, 2021). "PEAK1 protein was highly expressed and co-localized in CD31-positive vessels in breast cancer tissues compared to adjacent non-cancerous tissues." (PMID 29872538, 2018).
pancreatic cancer (16 papers, 2012 to 2025). "Forced PEAK1 expression can cause cell cycle deregulation and resistance to chemotherapy in pancreatic cancer cells." (PMID 34554318, 2022). "It has recently been found that PEAK1 overexpression is significantly associated with advanced clinical stage and poor prognosis in colon cancer and pancreatic cancer." (PMID 34554318, 2022). "PEAK1 expression is associated with metastasis and proliferation in many cancer types, such as colorectal cancer, lung cancer and pancreatic cancer." (PMID 34554318, 2022). "PEAK1 is upregulated in pancreatic cancer and has been associated with tumor invasion and metastasis." (PMID 34554318, 2022). "Overexpression of Pseudopodium enriched atypical kinase 1 (PEAK1/Sgk269), a protein discovered in the pseudopodia of migrating cells, is also found in colorectal cancer and pancreatic cancer." (PMID 34554318, 2022). "Altering PEAK1 expression can interfere with tumor formation and metastasis in pancreatic cancer cells in vivo, indicating that PEAK1 plays an important role in pancreatic cancer growth and metastasis." (PMID 34554318, 2022). "PEAK1 regulates focal adhesion dynamics and integrin signaling to the actin cytoskeleton in breast and pancreatic cancer cells." (PMID 29872538, 2018). "We have previously reported that PEAK1 kinase is essential for the initiation and progression of pancreatic cancer." (PMID 27602776, 2017). "The viability of this approach is supported by our previous work demonstrating that PEAK1 promotes the in vivo growth of both breast and pancreatic cancer cells." (PMID 26267863, 2015). "NKF3 or PEAK1 promotes anchorage independent growth and tumour progression in pancreatic cancer cells transplanted in mice." (PMID 22682234, 2012). "In pancreatic cancer epithelial cells, eIF5A is the upstream regulatory gene of PEAK1, and eIF5A may play a role by regulating PEAK1 signal." (PMID 33200656, 2020). "After PEAK1 silencing in human pancreatic cancer cells, tumor growth in nude mice was suppressed." (PMID 32167655, 2020). "Additionally, we’ve reported that the translation factor eIF5A drives PEAK1 protein production and can be targeted with the FDA-approved anti-fungal agent Cyclopirox Olamine (CPX) to both decrease cellular PEAK1 levels and abrogate pancreatic cancer cell growth." (PMID 26267863, 2015). "In vivo, PEAK1-dependent kindles induced by oncogenic KRas amplify the loop between SRC, PEAK1, and ERBB2 drive pancreatic cancer." (PMID 28871116, 2017). "In addition, knockdown of eIF5A significantly inhibited endogenous PEAK1 and YAP1 expression, leading to tumor initiation in pancreatic cancer." (PMID 33200656, 2020). "Moreover, in pancreatic cancer, KRAS activates Src in a pseudopodium-enriched atypical kinase 1 (PEAK1)-dependent manner or directly cooperates with Src, leading to metastatic tumor growth, therapy resistance, and accelerated tumorigenesis." (PMID 29455661, 2018). "Recently, PEAK1 was shown to interact with and regulate YAP1/TAZ in pancreatic cancer cells." (PMID 29872538, 2018). "This identified PEAK1, BMPR2, COL4A1 and ZEB1 as ITGA1 co-expressors in pancreatic cancer and suggested that ITGA1 may play a role in regulating TGFβ responses in pancreatic cancer." (PMID 28855593, 2017). "Pseudopodium-enriched atypical kinase 1 (PEAK1), a novel non-receptor tyrosine kinase, has been demonstrated to act as an oncogenic regulator in breast and pancreatic cancers." (PMID 30038287, 2018).
lung carcinoma (7 papers, 2018 to 2025). "Our data show that PEAK1 is significantly increased in lung cancers, and that its overexpression is associated with tumor metastasis." (PMID 30038287, 2018). "The expression of PEAK1 was obviously higher in lung cancer tissues than in normal tissues, and positively associated with lymph node (LN) metastasis in clinical specimens." (PMID 30038287, 2018). "In lung cancer cells, enforced PEAK1 expression induces EMT via activating extracellular signal-regulated kinase-1/2 (ERK1/2) and Janus kinase-2 (JAK2) signaling." (PMID 34365903, 2021). "Then, we had confirmed that PEAK1 was significantly upregulated in lung cancer tissues, and correlated with a higher tumor node metastasis stage." (PMID 30038287, 2018). "Here, we observed that ectopic PEAK1 expression promoted lung cancer cell migration and invasion, while PEAK1 knockout resulted in suppressed cell migration and invasion." (PMID 30038287, 2018). "The level of PEAK1 protein in five human lung cancer cell lines (H1975, H1299, H446, 95D, and A549) was detected using western blot analysis." (PMID 30038287, 2018). "In this study, we show that PEAK1 overexpression promotes lung cancer metastasis, EMT and EMT-related traits through regulating ERK1/2 and Janus kinase-2 (JAK2) signaling." (PMID 30038287, 2018). "As results, overexpressing of PEAK1 enhanced 95D and H1299 cell migration and invasion, whereas PEAK1 knockout reduced lung cancer cell migration and invasion." (PMID 30038287, 2018). "To investigate the possible pathways underlying the participation of PEAK1 in EMT and metastasis in lung cancer, we applied western blot analysis." (PMID 30038287, 2018). "Moreover, overexpression of inactive tyrosine protein kinase PEAK1 can modulate anus kinase-2 and extracellular signal-regulated kinase-1/2, which was involved metastasis of tumors in lung cancers." (PMID 34500744, 2021). "Next, we assessed PEAK1 protein expression patterns in lung cancer samples from patients." (PMID 30038287, 2018). "It would be interesting to examine whether the PEAK1 expression status in lung cancer can mediate the CSC phenotype and predict the response to chemotherapy." (PMID 30038287, 2018). "It is important to determine in future studies whether the expression of PEAK1 protein has any prognostic value in lung cancer patients." (PMID 30038287, 2018). "Targeting PEAK1-mediated molecular mechanisms might be an effective therapeutic strategy for EGFR-TKI-based treatments in certain lung cancer subsets." (PMID 30038287, 2018). "One plausible explanation is that the expression and function of PEAK1 might be affected by disordered estrogen secretion in breast and lung cancers." (PMID 30038287, 2018). "Moreover, the levels of PEAK1 protein were obviously higher in the clinical lung cancer samples than the adjacent normal tissues, and PEAK1 overexpression was obviously associated with LN metastasis." (PMID 30038287, 2018). "PEAK1 overexpression contributes to EMT and tumour metastasis by activating ERK1/2 and JAK2 signalling in lung cancer." (PMID 32244796, 2020). "Ding et al36 showed that PEAK1 activated the ERK1/2 and JAK2 signaling pathways and promoted the malignant biological behaviors of lung cancer cells." (PMID 32167655, 2020). "Our findings reveal that PEAK1 overexpression contributes to activation of the ERK1/2 and JAK2 pathways and promotes EMT in a lung cancer subset." (PMID 30038287, 2018). "However, the role of PEAK1 in the progression and metastasis of lung cancer is still unknown." (PMID 30038287, 2018). "Further analysis revealed that the staining score of PEAK1 was obviously higher in primary sites of lung cancer with LN metastasis than in those of non-metastatic lung cancer and in normal samples." (PMID 30038287, 2018).
lung carcinoma (continued). "According to the established principles for evaluating immunostaining, the rate of PEAK1-positive staining was significantly higher in the human lung cancer tissues than the adjacent non-tumor tissues." (PMID 30038287, 2018). "Our findings highlight a newer mechanism for PEAK1 in regulating EMT and metastasis in lung cancer, which might serve as a therapeutic target for lung cancer patients." (PMID 30038287, 2018). "Moreover, PEAK1 upregulation markedly enhanced the activation of extracellular signal-regulated kinase-1/2 (ERK1/2) and Janus kinase-2 (JAK2) signaling in lung cancer cells." (PMID 30038287, 2018). "To explore whether PEAK1 is overexpressed in lung cancer tissues, we analyzed the expression of PEAK1 protein in 70 lung cancer and 34 adjacent non-tumor tissues." (PMID 30038287, 2018). "However, the role of PEAK1 in the growth and metastasis of lung cancer has not been previously investigated." (PMID 30038287, 2018). "Indeed, PEAK1 expression was higher in human lung cancer tissues than adjacent non-tumor tissues." (PMID 30038287, 2018). "However, it is not clear whether the TGF-β/PEAK1 pathway is involved in the EMT process in lung cancer." (PMID 30038287, 2018). "In addition, PD98059 and/or AZD1480 can reduce the PEAK1-enhanced migration, invasion and EMT of NSCLC cells, suggesting that targeting the ERK1/2 and JAK2 pathways could potentially be used to treat PEAK1-overexpressing lung cancer in combination with standard chemotherapy." (PMID 30038287, 2018).
colon carcinoma (5 papers, 2010 to 2025). "Our studies have shown that high PEAK1 expression is associated with poor overall survival in colon cancer." (PMID 29449544, 2018). "PEAK1 overexpression suppressed colon cancer cell growth, invasion and metastasis in vitro and in vivo, whereas knockout had the opposite effects." (PMID 34554318, 2022). "Here, we show that PEAK1 is significantly upregulated in both colon and rectal cancer, and high PEAK1 expression predicts poor survival in colon cancer." (PMID 29449544, 2018). "Kaplan–Meier analysis showed that high levels of PEAK1 expression were correlated with poor overall survival in colon cancer." (PMID 29449544, 2018). "Finally, understanding the upstream regulators of PEAK1 and why it is upregulated in human colon cancers (and whether it is also upregulated in other human cancers) will likely help clinical oncologists understand disease progression." (PMID 21301050, 2010). "To further investigate the link between PEAK1 and ZO-1, we created PEAK1 CRISPR-knockout Caco-2 cells, a colon carcinoma cell commonly used for studying tight junctions." (PMID 40707483, 2025). "For example, miR-19a inhibits colon cancer angiogenesis by targeting KRAS and VEGFA, and miR-181d reduces cell proliferation, migration, and invasion by triggering PEAK1, a downstream regulator of the EGFR/KRAS pathway." (PMID 36960218, 2023). "Here, we found that PEAK1 is overexpressed in CRC tissues and that high PEAK1 expression predicts poor survival in colon cancer but not rectal cancer." (PMID 29449544, 2018).
colorectal cancer (5 papers, 2018 to 2022). A primary or metastatic malignant neoplasm that affects the colon or rectum. "In colorectal cancer cells, silencing PEAK1 inhibits cell proliferation, migration, and invasion in vitro and inhibits the growth of tumor xenografts in nude mice." (PMID 34365903, 2021). "PEAK1 is upregulated in multiple human malignancies and has been associated with tumor invasion and metastasis, but little is known about the role of PEAK1 in colorectal cancer (CRC) progression." (PMID 29449544, 2018). "Huang et al37 also showed that PEAK1 expression was high in colorectal cancer tissues and that PEAK1 silencing could inhibit proliferation, migration, and invasion of colorectal cancer cells and significantly attenuate EGF‐induced p‐ERK1/2 expression levels." (PMID 32167655, 2020).
diabetes (3 papers, 2024 to 2025). "Furthermore, a number of genes in this set (Peak1, Astn2, Bcar1, Ctnnal1, Ppfibp2) is associated with significant diabetes-related risk loci." (PMID 40667025, 2025). "At present, the research on PEAK1 is more focused on its role in tumor metastasis and invasion, so the research on PEAK1 and diabetes, especially T2DM, needs further discussion." (PMID 38915894, 2024). "Several genes that initially appeared significant without correction—such as PEAK1 for diabetes, TRIM10 for schizophrenia, and CCDC57 for chronic kidney disease—fell below the Bonferroni significance threshold after correction, underscoring the importance of this adjustment." (PMID 37904952, 2024).
pancreatic ductal adenocarcinoma (3 papers, 2018 to 2022). An infiltrating adenocarcinoma that arises from the epithelial cells of the pancreas. "Pseudopodium-enriched atypical kinase one, SGK269 (PEAK1) was identified as a potential biomarker for pancreatic ductal adenocarcinoma (PDAC)." (PMID 35590912, 2022).
triple-negative breast carcinoma (3 papers, 2020 to 2025). An invasive breast carcinoma which is negative for expression of estrogen receptor (ER), progesterone receptor (PR), and human epidermal growth factor receptor 2 (HER2). "Of particular interest, high PEAK1 expression occurs in triple negative breast cancer (TNBC) and pancreatic cancer, two cancers associated with poor prognosis and limited targeted therapeutic options." (PMID 39984440, 2025). "The PEAK family of pseudokinases, comprising PEAK1-3, play oncogenic roles in several poor prognosis human cancers, including triple negative breast cancer (TNBC)." (PMID 39984440, 2025). "In this study, the authors show that AXL activation can control focal adhesion dynamics via PEAK1 and that AXL-mediated PEAK1 phosphorylation is required for metastasis of triple negative breast cancer cells in vivo." (PMID 32681075, 2020).
colorectal tumors (2 papers, 2021 to 2023). "In this survey, we examined expression of circ0009910/miR-145-5p/PEAK1 axis in fifty pairs of colorectal tumor samples and their adjacent tissues." (PMID 34479583, 2021). "Moreover, significant decrease of miR-145-5p (P value < 0.0001) and increase of PEAK1 (P value < 0.0001) levels were observed in colorectal tumors compared with adjacent tissues." (PMID 34479583, 2021). "Also, expressions of miR-145-5p and PEAK1 in colorectal tumors compared with adjacent tissues were down- and upregulated, respectively." (PMID 34479583, 2021).
gastric cancer (2 papers, 2016 to 2022). A primary or metastatic malignant neoplasm involving the stomach. "However, a study in gastric cancer showed 71.1% negative expression of PEAK1 in the cancer tissues and indicated that loss of PEAK1 may activate EMT and promote cancer development." (PMID 27916872, 2016). "However, PEAK1 is downregulated in gastric cancers, and higher PEAK1 expression was correlated with non-lymph node metastases and a good prognosis." (PMID 34554318, 2022).
lymph node metastasis (2 papers, 2018 to 2022). "In addition, we found that PEAK1 was markedly upregulated in patients with lymph node metastasis compared to patients without." (PMID 29449544, 2018).
bladder cancer (1 paper, 2024). "Gstt2, Gphn, Plec Cmss1, Ahnak, Slc2a1, Gsta4, Kras, Peak1, and Hmga2 were associated with worse overall survival in bladder cancer patients, and the association was significant for Gstt2 and Ahnak." (PMID 39769061, 2024). "Ankfn1, Gstt2, Plec, Gphn, Fmo5, Cmss1, Ahnak, Mecom, Slc2a1, Gsta4, Kras, Peak1, and Hmga2 were associated with worse disease-free survival in bladder cancer patients." (PMID 39769061, 2024).
breast tumor (1 paper, 2021). "We next asked whether PEAK1-expressing CAFs or MSCs could affect breast tumor growth and progression in the Gallus gallus embryo chorioallantoic membrane (CAM) in vivo model." (PMID 34239043, 2021).